NIFKP3 (NIFK pseudogene 3)
Synonyms: MKI67IPP3
Gene: Transcribed processed pseudogene on chromosome 12 (7,604,350 to 7,605,214, reverse strand). Ensembl gene ENSG00000256331.
Diseases named in the same sentence as NIFKP3 in open-access papers:
NIFKP3 is named in the same sentence as 1 disease in open-access papers, as found by Europe PMC text mining. Sharing a sentence is not in itself a finding about the gene and the disease. The quoted sentences say what the papers report.
metabolic syndrome (1 paper, 2023). A cluster of metabolic risk factors for CARDIOVASCULAR DISEASES and TYPE 2 DIABETES MELLITUS. "Our results show that cg25828445, annotated to NIFKP3 gene, was significantly hypermethylated in patients who remained with metabolic syndrome after bariatric surgery." (PMID 37834223, 2023).